SIRT4 (sirtuin 4)
Diseases named in the same sentence as SIRT4 in open-access papers (continued):
Sharing a sentence is not in itself a finding about the gene and the disease.
laryngeal squamous cell carcinoma (1 paper, 2023). A squamous cell carcinoma that arises from the larynx. "At the same time, SIRT4 overexpression inhibited the proliferation and migration of laryngeal squamous cell carcinoma cells." (PMID 40625712, 2023). "In a study examining SIRT4 in 168 groups of laryngeal squamous cell carcinoma tissues and normal paraneoplastic tissues, SIRT4 was expressed lower in laryngeal squamous cell carcinoma tissues compared to normal paraneoplastic tissues." (PMID 40625712, 2023). "It was significantly associated with histological grade, T‐classification, clinical stage, lymph node metastasis, and recurrence in laryngeal squamous cell carcinoma patients, while in vitro experiments showed that knockdown of SIRT4 promoted LSCC cell proliferation and migration." (PMID 40625712, 2023).
lymphoma (1 paper, 2020). A malignant (clonal) proliferation of B- lymphocytes or T- lymphocytes which involves the lymph nodes, bone marrow and/or extranodal sites. "In a mouse model, SIRT4 deletion accelerated the formation of lymphoma and mortality in Em-Myc transgenic mice." (PMID 33585187, 2020).
myocardial infarction (1 paper, 2025). Gross necrosis of the myocardium, as a result of interruption of the blood supply to the area, as in coronary thrombosis. "In this study, we found that among sirtuin family members, Sirt4 and Sirt5 expression increased with age and decreased post‐myocardial infarction (MI) in neonatal mice." (PMID 40842073, 2025).
neuropathy (1 paper, 2024). A disorder affecting the nervous system that manifests with pain, tingling, numbness, and/or muscle weakness. "Given our observation of mitochondrial alterations in PDN rats and the lack of correlation between SIRT4 and SIRT5 with DRG or neuropathy, we have chosen to focus our investigation on SIRT3." (PMID 38572816, 2024).
non-small cell lung carcinoma (1 paper, 2022). A group of at least three distinct histological types of lung cancer, including non-small cell squamous cell carcinoma, adenocarcinoma, and large cell carcinoma. "Indeed, loss of SIRT4 increased non-small cell lung cancer cell growth, migration, and invasion." (PMID 35356277, 2022). "One study looked at SIRT4/ERK/DRP1 in non-small cell lung cancer tumor progression." (PMID 35356277, 2022).
oesophageal cancer (1 paper, 2020). "SIRT3 silencing inhibited proliferation and induced apoptosis in oesophageal cancer cells, whereas SIRT4 silencing augmented proliferation and migration of ESCC cells." (PMID 32429269, 2020). "Overall, and except for SIRT4, HDACs seem to play an oncogenic role in oesophageal cancer." (PMID 32429269, 2020).
squamous cell carcinoma (1 paper, 2020). A carcinoma arising from squamous epithelial cells. "In addition, the proportion of SIRT4 down-regulation in adenocarcinoma (52/84, 61.9%) was higher than that in squamous cell carcinoma (18/49, 36.73%)." (PMID 33585187, 2020).
status epilepticus (1 paper, 2024). Status epilepticus is defined as a continuous seizure lasting more than 30 min, or two or more seizures without full recovery of consciousness between any of them. "Sirt4–/– mice exhibited more frequent and intense symptoms, including outstretched hind limbs and front paws tucked under the chin, which suggest death during an episode of status epilepticus upon PTZ administration." (PMID 38346975, 2024).
systemic lupus erythematosus (1 paper, 2026). An autoimmune multi-organ disease typically associated with vasculopathy and autoantibody production. "Moreover, SIRT4 inhibitor treatment attenuates type I interferon signaling in Trex1-deficient cells and in peripheral blood mononuclear cells (PBMCs) from patients with systemic lupus erythematosus (SLE)." (PMID 41634380, 2026).
tumor (115 papers, 2012 to 2025). "SIRT4, largely associated with metabolic regulation, generally exhibits tumor-suppressive functions in CNS tumors." (PMID 40710366, 2025). "Despite these observations, the precise mechanisms underlying the tumor-promoting effects of SIRT4 remain poorly understood." (PMID 40384857, 2025). "Like many of the other members of SIRT family, SIRT4 has been associated with tumorigenesis; in particular, SIRT4 inhibits the mitochondrial glutamine metabolism in cancer cells, acting as a tumor suppressor." (PMID 39683482, 2024). "Remarkably, Myc-induced lymphomagenesis in mice is accelerated by SIRT4 loss, highlighting its tumor-suppressive function." (PMID 38773972, 2024). "Tumor suppressive properties presented by SIRT4 are associated with inhibition of glutamine catabolism caused by DNA damage." (PMID 37630770, 2023). "As a newly discovered molecule, mitochondrial protein Sirtuin 4 (SIRT4) has been linked to alternative glutamine metabolism and regulation of the tumour microenvironment." (PMID 38136342, 2023). "Further ultrastructural evidence of autophagy in mouse tumor tissues confirmed that the AMPKα was implicated in the induction of autophagy by SIRT4 in PDAC cells." (PMID 36209169, 2023). "SIRT4 has been reported to be a therapeutic target that has both oncogenic and tumor suppressor effects in cancers; however, the underlying mechanism is still a matter of debate." (PMID 36291902, 2022). "For instance, high expression of SIRT1 and SIRT7 is highly associated with poor survival, whereas low tumor levels of SIRT4 predicts a decreased survival time in HCC patients." (PMID 36581622, 2022). "A previous study indicated that SIRT4 silencing in tumour‐associated macrophages promotes HCC development." (PMID 34272822, 2021). "In vivo, evidence showed similar results that BPTES treatment successfully reversed the tumor-promoting effects by SIRT4 deficiency." (PMID 32863939, 2020). "Lower levels of Sirt4 protein expression in tumor tissues are often associated with worse pathological grading and reduced survival in cancer patients, and Sirt4 KO mice display an increased incidence of spontaneous tumors." (PMID 32373514, 2020). "Altogether, these studies indicate that overexpression of HDAC proteins (except for SIRT4) seems to be a meaningful event in oesophageal carcinogenesis, favouring tumour progression and associating with poor survival." (PMID 32429269, 2020). "SIRT-4 is a tumor suppressor that is reduced in various carcinomas, and reduced SIRT-4 protein expression is associated with poor prognosis." (PMID 33412753, 2020). "Therefore, the reduced expression of SIRT4 in non-tumor cells leads to the accumulation of cell mutations and DNA damage, which contributes to the formation of tumors." (PMID 38773972, 2024). "We found by immunohistochemistry that SIRT4 protein levels were reduced in BLCA and that lower SIRT4 levels were associated with larger tumor volumes, later T-staging and later AJCC staging in BLCA patients and were an independent prognostic factor in BLCA patients." (PMID 37301821, 2023). "Overall, this suggests loss of SIRT4 positively influences tumor progression." (PMID 35356277, 2022). "The tumor-suppressive role of SIRT4 is also implicated in HCC31,32." (PMID 33931611, 2021).
tumor (continued). "Taken together, the reduced SIRT4 expression in the tumor/peritumor tissues and HCC cell lines compared with normal tissues and cell lines suggested a putative tumor-suppressive role of SIRT4 in HCC, and its downregulation was associated with poor patient survival." (PMID 33931611, 2021). "In addition, the histopathologic analyses of these specimens revealed that a higher PAK6/ANT2 expression and a lower SIRT4 expression were significantly associated with the tumor size." (PMID 32194820, 2020). "It has been reported that SIRT4 may affect the inflammatory response, so its role in the tumour immune microenvironment, especially in tumour-associated macrophages (TAMs) was investigated next." (PMID 31744516, 2019). "In line with this, SIRT4 is able to suppress tumor formation, whereas the loss of SIRT4 enables tumor formation at least in part by elevated glutamine metabolism, loss of the metabolic checkpoint and as a consequence genomic instability accompanied by enhanced proliferation." (PMID 26426055, 2015). "Functional assays in the study show that SIRT4 inhibits migration, invasion, and proliferation, while promoting apoptosis, with this suppression mechanistically linked to the inhibition of glutamine metabolism, a critical pathway for sustaining tumor cell growth and invasiveness." (PMID 39796040, 2024). "The results showed that the tumor growth was suppressed when SIRT4 was overexpressed, while Pifithrin-α reversed this effect, and the Inauhzin could restore the tumor growth caused by SIRT4 depletion." (PMID 36209169, 2023). "Specifically, the expression level was measured to be (1.03 ± 0.23) in tumor tissues versus (1.45 ± 0.13) in normal tissues, indicating a clear downregulation of SIRT4 in cancerous cells." (PMID 40710366, 2025). "SIRT4 also exhibits tumor suppression effects in other cancers, such as thyroid cancer, colorectal cancer, and B-cell lymphoma." (PMID 41304967, 2025). "Overexpressing SIRT4 in human NB cell lines led to a significant reduction in cell proliferation, invasion, and migration, indicating that SIRT4 functions as a tumor suppressor." (PMID 40710366, 2025). "Here, we reported that SIRT4 was highly expressed in the voltage-gated calcium channel α2δ1 subunit-positive HCC tumor-initiating cells (TIC), and was upregulated by α2δ1-mediated calcium signaling." (PMID 40384857, 2025). "The consensus that SIRT4 suppresses tumor development through inhibition of glutamine metabolism suggests its potential as a novel biomarker and therapeutic target for malignancies." (PMID 39944690, 2025). "SIRT4, a mitochondrial sirtuin, plays a crucial role in maintaining mitochondrial metabolism essential for DNA damage repair and exhibits anti-tumor properties by inhibiting mitochondrial glutamine metabolism in response to cellular DNA damage." (PMID 40109870, 2025). "Mitochondria Sirtuins including SIRT4 erase a variety of posttranslational modifications from mitochondria proteins, leading to metabolic reprogramming that acts as a tumor suppressor, oncogenic promotor, or both." (PMID 40298941, 2025). "Their findings indicate that SIRT4 maintains CD8+ T cell chemotaxis and cytotoxic activity, and that inhibition of SIRT4 impairs T cell function, promoting tumor immune escape." (PMID 41425553, 2025). "The presented data highlight the tumor-suppressing effect of SIRT4 in the context of neoplasms originating from blood and bone marrow cells." (PMID 40149343, 2025). "As compared to healthy tissues, decreased mRNA levels of SIRT4 were observed in many neoplasms, including breast, stomach, thyroid, bladder, colon, and ovary cancers." (PMID 40149343, 2025). "SIRT4 exhibits tumor-suppressive functions in various cancers, such as prostate cancer, where it inhibits cell progression by modulating p21 nuclear translocation and glutamine metabolism." (PMID 40710366, 2025).
tumor (continued). "The mitochondrial SIRT4 directly interacts with CRAF and suppresses CRAF-MAPK signaling accompanied by reduced p-ERK1/2 levels, which provides evidence for an extra-mitochondrial tumor-suppressing mechanism of SIRT4." (PMID 39935431, 2025). "By impeding AKT phosphorylation, SIRT4 promotes the nuclear retention of the cell cycle inhibitor p21, thereby enforcing cell cycle arrest and stifling tumor cell division." (PMID 39796040, 2024). "In particular, SIRT4 inhibits, as a tumor suppressor, the metabolic gatekeepers pyruvate dehydrogenase and glutamate dehydrogenase, with particular significance for the regulation of glutamine metabolism in tumor cells." (PMID 38499327, 2024). "As PAK6 enhances ANT2 phosphorylation to inhibit apoptosis, it simultaneously destabilizes SIRT4, further tipping the balance toward tumor survival." (PMID 39796040, 2024). "SIRT4 is thought to act as a tumor suppressor by repressing glutamine metabolism in Myc-induced B cell lymphoma." (PMID 39372420, 2024). "It is believed that with the continuous progress of scientific research, SIRT4 will become a new target and direction in the field of tumor therapy." (PMID 38773972, 2024). "Considering these interrelated findings, in this study we investigated the molecular and functional interaction between the proto-oncogene C-RAF and the tumor suppressor SIRT4 in the context of MAPK signaling inhibition." (PMID 38499327, 2024). "Recent investigations reveal that SIRT4 expression is significantly reduced in PCa tissues compared to non-cancerous tissues, with lower levels correlating with more aggressive tumor phenotypes." (PMID 39796040, 2024). "Previous research demonstrated SIRT4's inhibition of tumor growth by targeting glutamine metabolism." (PMID 38773972, 2024). "In contrast, SIRT3 and SIRT4 primarily function as tumor suppressors by regulating cellular metabolism, cell cycle progression, and chromosomal stability, thereby counteracting tumorigenesis." (PMID 39796040, 2024). "Promotion of tumor formation in MEF cells and spontaneous tumor development in mice, including lung, liver, breast, and lymphomas, is seen with SIRT4 deficiency." (PMID 38773972, 2024). "Tumor-suppressive functions in CRC are exerted by SIRT4 through regulation of E-cadherin expression and inhibition of EMT via suppression of glutamine metabolism." (PMID 38773972, 2024). "It is well established in the literature that SIRT4 overexpression inhibits cell proliferation, among other cellular responses, in several tumor cell lines, most likely through inhibition of the MAPK pathway." (PMID 38499327, 2024). "Reduced SIRT4 expression in human cancers correlates with increased cell transformation and tumor development, highlighting its role in tumor metabolism." (PMID 38773972, 2024). "Specifically, HDAC4, HDAC5, KAT2B, NCOA1, SIRT1, and SIRT4 had lower expression in tumor tissues across 14, 12, 18, 17, 16, and 12 cancer types, respectively." (PMID 39906742, 2024). "SIRT4 negatively regulates Warburg effects, such as inhibiting aerobic glycolysis, tumor growth and suppressing HIF-1α level in PANC-1 and MIA PaCa-2(pancreatic cancer cell lines)." (PMID 39372420, 2024). "Mitochondrial sirtuins (SIRT3–SIRT5) regulate metabolism, with SIRT3 and SIRT4 acting generally as tumor suppressors, while SIRT5’s role remains ambiguous across caner types." (PMID 39796040, 2024).
tumor (continued). "SIRT4, in contrast, exerts tumor-suppressive effects by inhibiting aerobic glycolysis and attenuating the proliferative signals in the mTOR pathway." (PMID 39682281, 2024). "Recent studies have demonstrated that SIRT4 inhibits tumor growth in pancreatic ductal adenocarcinoma through in vitro and in vivo experiments." (PMID 38773972, 2024). "This study proposed a novel extra-mitochondrial role of the tumor suppressor SIRT4 in negatively regulating the MAPK pathway by interacting with C-RAF kinase." (PMID 38499327, 2024). "PAK6, primarily located in the mitochondrial inner membrane, modulates SIRT4 stability through ubiquitin-mediated proteolysis, effectively decreasing its tumor-suppressive activity." (PMID 39796040, 2024). "Most studies have investigated the tumor suppressor function of SIRT4, but some studies have also confirmed that SIRT4 is also pro-carcinogenic, this is also related to the metabolic preferences of different cancers." (PMID 39479446, 2024). "Entinostat, a potent stimulator of SIRT4, demonstrates the promise of using SIRT4-targeted therapies to impair tumor growth, offering a novel clinical intervention for this aggressive disease." (PMID 39682281, 2024). "SIRT4 has been found with a notable impact on the inhibition of tumor metabolism, specifically in relation to glutamine metabolism, indicating a potential anti-tumor effect." (PMID 38702756, 2024). "SIRT4’s tumor-suppressive role in PCa is further supported by its capacity to modulate post-translational modifications, particularly through ADP-ribosylation." (PMID 39796040, 2024). "UHRF1, an epigenetic regulator known for silencing tumor suppressor genes, negatively impacts SIRT4 levels, thereby facilitating cancer cell proliferation and metabolic reprogramming." (PMID 39682281, 2024). "Some studies have shown that SIRT4 mainly exerts tumor-suppressive function and is correlated with a worse prognosis in multiple cancers." (PMID 36209169, 2023). "Studies that have focused on the association between SIRT4 activity and tumorigenesis emphasize the role of SIRT4 as a tumor suppressor." (PMID 37630770, 2023). "In conclusion, our research confirmed the tumor-suppressive function of SIRT4 in PDAC using a range of molecular, cell biology, animal, and clinical approaches." (PMID 36209169, 2023). "Our study suggests that SIRT4 is an independent prognostic factor for BLCA and that SIRT4 plays a tumor suppressor role in BLCA." (PMID 37301821, 2023). "We found that WDR79 depletion increased SIRT4 expression by suppressing UHRF1 expression, and inhibition of SIRT4 expression reversed the anti-tumor effect of WDR79 in PC." (PMID 36712589, 2023). "Typically, SIRT4 senses energy metabolism after DNA damage blocks the cell cycle and inhibits tumor formation by blocking glutamine metabolism." (PMID 40625712, 2023). "Nucleosome-localized sirtuin 4 (SIRT4) was found to function as an oncogene and tumor suppressor gene in different tumors." (PMID 37301821, 2023). "Among them, SIRT4 is a mitochondrial negative regulator of aerobic glycolysis, and its high expression can inhibit tumor proliferation or increase the sensitivity of tumor cells to chemotherapy drugs in PC." (PMID 36712589, 2023). "SIRT4, a sirtuin localized in the mitochondria, is a tumor suppressor present in various tumor models." (PMID 36982568, 2023). "We found that low levels of SIRT4 staining were more likely to be seen in patients with larger tumor size, later T-stage, and later AJCC stage (P values of 0.02, 0.02 and 0.02, respectively)." (PMID 37301821, 2023). "We then performed immunoblot assays to detect the effects of SIRT4 on the anti-tumor effect of WDR79 in PDAC." (PMID 36712589, 2023).